TP53TG5 (TP53 target 5)
Synonyms: C20orf10; CLG01; dJ453C12.5
Tractability: PROTAC: ubiquitination databases record sites on it.
Gene: Protein-coding gene on chromosome 20 (45,372,557 to 45,407,889, reverse strand). Ensembl gene ENSG00000124251.
Subcellular location: Cytoplasm; Nucleus
Subcellular location (Human Protein Atlas): Nucleoli; Nucleoli rim; Mitotic chromosome
Gene Ontology:
Molecular function: protein binding
Biological process: intracellular signal transduction; negative regulation of cell growth
Cellular component: chromosome; nucleolus; nucleus; cytoplasm
Genetic constraint (gnomAD): Loss-of-function variants: 15 observed, 27.42 expected, observed/expected ratio (o/e) 0.55, 90% interval 0.37 to 0.84. The upper end of that interval is the gene's LOEUF score, 0.84, which puts it in group 3 of 6, group 1 being the genes least tolerant of losing a copy. Missense variants: 274 observed, 304.47 expected, observed/expected ratio (o/e) 0.9, 90% interval 0.81 to 1. Synonymous variants: 100 observed, 115.28 expected, observed/expected ratio (o/e) 0.87, 90% interval 0.74 to 1.02.
Homologues: Orthologues: chimpanzee TP53TG5 (98% identical), macaque TP53TG5 (92% identical), dog TP53TG5 (52% identical), mouse Trp53tg5 (47% identical), rat Tp53tg5 (47% identical).
Diseases named in the same sentence as TP53TG5 in open-access papers:
TP53TG5 is named in the same sentence as 4 diseases in open-access papers, as found by Europe PMC text mining. Sharing a sentence is not in itself a finding about the gene and the disease.
glioblastoma (1 paper, 2016). The most malignant astrocytic tumor (WHO grade IV).
TP53TG5 also shares sentences with these, for which no sentence is quoted: cancer (2 papers); ovarian carcinoma (1); tumor (1).